RNU6-1238P (RNA, U6 small nuclear 1238, pseudogene)
Gene: Small nuclear RNA gene on chromosome 11 (67,395,210 to 67,395,311, reverse strand). Ensembl gene ENSG00000253024.
Homologues: Orthologues: guinea pig U6 (63% identical), dog U6 (62% identical), mouse Gm26373 (62% identical). Paralogues in human: RNU6-1082P (73% identical), RNU6-1181P (73% identical), RNU6-30P (73% identical), RNU6-651P (73% identical), RNU6-797P (73% identical), RNU6-862P (73% identical), RNU6-1 (72% identical), RNU6-1145P (72% identical), RNU6-11P (72% identical), RNU6-1209P (72% identical), RNU6-140P (72% identical), RNU6-15P (72% identical), and 1284 more.